CD4 (CD4 molecule)
Diseases named in the same sentence as CD4 in open-access papers (continued):
Sharing a sentence is not in itself a finding about the gene and the disease.
schwannoma (2 papers, 2024 to 2025). A benign, usually encapsulated slow growing tumor composed of Schwann cells. "Proliferating immune cells adjacent to spike-in landmark myeloid or lymphoid clusters were greater in immune-enriched compared to neural crest schwannomas, including memory and effector CD4 and CD8 T cells, γδT cells, NK cells, macrophages, and conventional and plasmacytoid dendritic cells." (PMID 38216587, 2024).
scrapie (2 papers, 2011 to 2019). A fatal disease of the nervous system in sheep and goats, characterized by pruritus, debility, and locomotor incoordination. "Having previously shown that PrP-sensitized polyclonal T cells attenuate scrapie evolution, we undertook to confirm those conclusions with transgene-bearing CD4+ T cells." (PMID 21909267, 2011).
septic peritonitis (2 papers, 2014 to 2024). Septic peritonitis is an inflammatory condition of the peritoneum that occurs secondary to microbial contamination. "Thus, a particularly high loss of CD4+ T-cells in LPS-dependent SIRS and septic peritonitis stands in contrast to a more pronounced drop of CD8+ T-cells in CpG-sparked SIRS." (PMID 25541945, 2014). "Using a murine model of septic peritonitis in the context of chronic alcohol exposure, we investigated the T cell coinhibitory marker CTLA-4 and found an increase in its expression within the CD4+ T cell compartment." (PMID 38226924, 2024).
sexual dysfunction (2 papers, 2024). Disturbances in sexual desire and the psychophysiologic changes that characterize the sexual response cycle and cause marked distress and interpersonal difficulty. "With respect to HIV-related factors, a high CD4 count (≥ 500) was the only one with a statistically significant association to sexual dysfunction (1.42 (1–2.01; p = 0.05)." (PMID 38451991, 2024).
skin abscess (2 papers, 2010 to 2024). "Here we provide evidence that S. aureus WTA and CP are both crucial for SSTIs provoked by S. aureus, and that WTA induces skin abscesses through MHC II–dependent activation of CD4+ T cells." (PMID 20949105, 2010). "Taken together, we present a novel function of WTA as a ZPS that can modulate CD4 T cell-dependent development of skin abscesses in mice." (PMID 20949105, 2010).
small cell carcinoma (2 papers, 2018 to 2023). A neuroendocrine carcinoma composed of small malignant cells which are often said to resemble "oat cells" under the microscope. "Interestingly, suppression of LSD1 simultaneously promoted the infiltration of CD8+, CD4+, CD4+CD8+ double positive T cells and CD56+ NKT cell infiltration in small cell carcinoma of the ovary hypercalcemic type (SCCOHT)." (PMID 37483603, 2023).
squamous cell tumor (2 papers, 2023 to 2024). "We explored whether the response to ICB of an aggressive low-TMB squamous cell tumor could be improved through combination immunotherapy using functionally defined NeoAg as targets for endogenous CD4+ and CD8+ T cells." (PMID 37655661, 2023). "recently discovered several CD4+ and CD8+ T cell epitopes on an aggressive low-TMB squamous cell tumor cell line." (PMID 39040850, 2024).
stomatitis (2 papers, 2022 to 2024). Inflammation of the oral mucosa due to local or systemic factors. "AZT has been shown to reduce viral load, with improvements in immunologic status (including CD4+/CD8+ ratios), quality of life, life‐expectancy and clinical status, particularly in neurologic presentations of FIV or FIV‐associated stomatitis." (PMID 35578381, 2022).
thoracic aortic aneurysm (2 papers, 2018 to 2024). An aneurysm formed in the wall of the proximal portion of the descending aorta proceeding from the arch of the aorta. "We unveiled that the circulating levels of the MAIT, CD4+IL−17A+, and NKT T cell subsets were significantly reduced in bicuspid valve disease cases, when compared to tricuspid aortic valve cases in either the presence or the absence of thoracic aortic aneurysm." (PMID 29854087, 2018).
thyroid abnormalities (2 papers, 2019 to 2022). "Age and gender are crucial elements in the onset of thyroid abnormalities, together with T CD4+ cell nadir." (PMID 31857648, 2019).
tick infestation (2 papers, 2017 to 2021). Infestations with soft-bodied (Argasidae) or hard-bodied (Ixodidae) ticks. "We here demonstrate that skin CD4+ memory T cells play an essential role in acquired protective immunity against tick infestations through the production of interleukin-3 (IL-3) that in turn induces basophil recruitment to the tick re-infestation site." (PMID 29085376, 2017). "Skin CD4+ memory T cells play an essential role in acquired protective immunity to tick infestation through the production of IL-3 that in turn induces basophil recruitment to the site of tick re-infestation." (PMID 29085376, 2017).
transient ischemic attack (2 papers, 2015 to 2022). A brief attack (from a few minutes to an hour) of cerebral dysfunction of vascular origin, with no persistent neurological deficit. "Predictors of the absolute number or fraction of immune cells in patients with acute ischemic stroke/transient ischemic attack (univariate analysis; (CD4+CD8− T cells, CD8+CD4− T cells, FoxP3 Treg)." (PMID 26512654, 2015). "Predictors of fractions of CD4+CD8− and CD8+CD4− T cells in patients with acute ischemic stroke/transient ischemic attack (multivariate analysis)." (PMID 26512654, 2015).
type IV hypersensitivity reaction (2 papers, 2024 to 2025). "The CHS reaction is mediated by CD4+T cells producing IL-17A and IFN-γ and is classified as a type IV hypersensitivity reaction, which characterizes many autoimmune disorders." (PMID 39247190, 2024).
uterine carcinosarcoma (2 papers, 2020 to 2022). A usually aggressive malignant neoplasm arising from the uterine corpus and less often the cervix. "We found that all the TCGA cancers excluding UCS (Uterine Carcinosarcoma) showed statistical positive correlation between high LMNB1 expression and the immune infiltration of CD4+ Th2 cells based on XCELL algorithm." (PMID 35241075, 2022).
uterine fibroids (2 papers, 2019 to 2023). "Given regulatory T (Treg; CD4+CD25+CD127−), helper T (Th; CD3+CD4+CXCR5−), and follicular helper T (Tfh; CD3+CD4+CXCR5+) cells are all differentiated from the naïve CD4+ T cells, we further compared the distribution of these cells between patients with uterine leiomyoma and healthy controls." (PMID 31772580, 2019). "We also found CD4/CD8 CM cells increased in patients with uterine leiomyoma." (PMID 31772580, 2019). "The present study aimed to analyze the characteristics of immune function and clinical significance of circulating CD4/CD8 T, NK, and γδ T cells in reproductive females with uterine leiomyoma." (PMID 31772580, 2019). "Our results demonstrated that compared with healthy controls, CD4/CD8 CM, Treg, and Tfh cells were significantly increased and that functional NK and γδ T cells were notably attenuated in patients with uterine leiomyoma." (PMID 31772580, 2019).
vulvar intraepithelial neoplasia (2 papers, 2015 to 2024). Intraepithelial neoplasia of the vulvar squamous epithelium. "Premalignant conditions include cervical intraepithelial neoplasia (CIN) and vulvar intraepithelial neoplasia (VIN) have so far shown the highest immunogenicity in terms of CD4 +and CD8 +T cell responses and clinical responses." (PMID 39127974, 2024).
X-linked hyper-IgM syndrome (2 papers, 2010 to 2019). "An example of this can be found in one of the original descriptions of mutations in CD40LG, which reported detectable expression of CD40L on activated CD4+ T cells from one patient with X-linked hyper-IgM syndrome despite the presence of a predicted inactivating mutation." (PMID 31552044, 2019). "Thus, males with X-linked hyper IgM syndrome could be identified by the inability of their CD4+ T cells to upregulate expression of functional CD40L following anti-CD3/CD28 or PMA/ionomycin-mediated activation." (PMID 31552044, 2019).
yang deficiency (2 papers, 2013 to 2023). Yang deficiency is a concept from traditional Chinese medicine. "Yang-deficiency constitution is related to liver toxicity, nephrotoxicity, side effects, and total mortality, but Yang deficiency is not related to CD4+, CD8+, and annual changes." (PMID 36700040, 2023). "Association was neither identified in CD4 (Kruskal-Wallis rank sum test P = 0.54) nor CD8 (Kruskal-Wallis rank sum test P = 0.34) reconstitution pattern (all the 16 clusters) with Yang deficiency." (PMID 24489581, 2013). "Yang deficiency was neither associated with annual change nor Nadir value of CD4 or CD8 count." (PMID 24489581, 2013).
Acinic cell carcinomas (1 paper, 2025). "Acinic cell carcinomas (ACC) showed enriched CD4+/CD8+ T cells and antigen-presenting CAFs (apCAFs), indicating strong immune infiltration." (PMID 41083996, 2025).
acoustic neuroma (1 paper, 2011). A type of benign brain tumor that begins in the Schwann cells, which produce the myelin that protects the acoustic nerve - the nerve of hearing. "CD4+ T lymphocytes predominate in the endolymphatic sac, while CD8+ T lymphocytes are normally scanty, but the relationship between CD4+ and CD8+ T cells may be inverted in case of chronic antigen stimulation, as in the presence of acoustic neuroma." (PMID 22053211, 2011).
acquired thrombotic thrombocytopenic purpura (1 paper, 2019). Acquired thrombotic thrombocytopenic purpura is the non-hereditary form of thrombotic thrombocytopenic purpura (TTP), characterized by profound peripheral thrombocytopenia, microangiopathic hemolytic anemia (MAHA) and single or multiple organ failure of variable severity. "In clinical immunology and for research purposes, AAPCs represent a convenient platform to monitor CD4+ T cell responses in patients against allergens, autoantigens, or infectious antigens, as it was shown with the antigen ADAMTS13 involved in acquired thrombotic thrombocytopenic purpura." (PMID 31156634, 2019).
Acute hepatic failure (1 paper, 2019). Hepatic failure refers to the inability of the liver to perform its normal synthetic and metabolic functions, which can result in coagulopathy and alteration in the mental status of a previously healthy individual. "In this context, accelerated NKT cell activation in CD160−/− mice could be due to increased availability of HVEM on CD4+ T cells, which could, in turn, lead to severe inflammation and acute hepatic failure." (PMID 31332204, 2019).
acute pharyngitis (1 paper, 2022). An acute and painful inflammatory process that affects the pharynx. "Moreover, reduced CXCR3 expression observed on T cells during acute pharyngitis suggests that S. pyogenes infection promotes migration of CD4+ T cells from the blood." (PMID 35140232, 2022). "The hallmarks of acute pharyngitis are increased levels of monocyte and dendritic cell subsets, elevation of IL-1Ra, IP-10 and IL-18, activation of unconventional T cells, and migration of B cells and CD4+ T-cell subsets from the blood." (PMID 35140232, 2022).
adrenocortical adenomas (1 paper, 2021). "Interestingly, the CD4 T cells, B cells, and macrophages are mainly presented in two adrenal cortical adenomas (ACA_T1 and ACA_T2), while the CD8 T cells mostly resided in the microenvironment of other pheochromocytoma tumor and the peritumoral specimen." (PMID 34905486, 2021).
adult-onset Still disease (1 paper, 2019). A rare inflammatory multisystem disorder characterized clinically by fever of unknown origin, arthralgia or arthritis, hyperleucocytosis, and typical skin rash. "CD4+CD62L- and CD8+CD62L- cell proportions in whole PBL population were decreased in adult-onset Still’s disease (AOSD) compared to RA or healthy controls." (PMID 31614573, 2019).
aging (1 paper, 2022). A developmental process that is a deterioration and loss of function over time. "We were surprised to find that hub genes here correlate simultaneously with the activated B cell, activated dendritic cell, Gamma delta T cell, central memory CD4 + T cell and mast cell in pain and aging diseases, suggesting their immunity roles across the disorders." (PMID 36340779, 2022).
alcohol addiction (1 paper, 2019). "Patients with prevalent TB had higher tobacco (p < 0.0001) and alcohol addiction (p < 0.0001), lower Hb (p < 0.0001) and lower CD4 count at ART initiation (p < 0.0001) as compared to those without prevalent TB." (PMID 31409289, 2019).
alcoholic pancreatitis (1 paper, 2018). Acute or chronic inflammation of the pancreas due to excessive alcohol drinking. "In alcoholic pancreatitis, the CD4+T lymphocytes presented an AUC of 0.96, the CD19+ B lymphocytes showed an AUC of 0.91, the combination ofCD4+T and CD19+ B lymphocytes had an AUC of 0.91, and the AUC of the APACHE II score and Ranson score were 0.66 and 0.64, respectively." (PMID 30627533, 2018).
alexithymia (1 paper, 2021). An agnosia that is a deficiency in understanding, processing, or describing emotions. "Lymphocyte subset counts (CD4, CD8), in vitro production of interleukin 1β (IL-1β), IL-2, IL-4, and IL-10 by phytohemagglutinin stimulated peripheral blood lymphocytes, as well as serum cortisol levels, were compared between women with and without alexithymia." (PMID 34987425, 2021).
alpha-mannosidosis (1 paper, 2020). Alpha-mannosidosis is an inherited lysosomal storage disorder characterized by immune deficiency, facial and skeletal abnormalities, hearing impairment, and intellectual deficit. "While in alpha‐mannosidosis, increased expression of LAMP‐1 was most pronounced in the CD4 and CD8 (T‐cell) compartment, increased LAMP‐1 expression was especially profound in the CD20 (B‐cell) compartment of patients with sialidosis." (PMID 32685355, 2020).
Alpha-thalassemia (1 paper, 2020). Alpha-thalassemia is an inherited hemoglobinopathy characterized by impaired synthesis of alpha-globin chains leading to a variable clinical picture depending on the number of affected alleles. "Unavailability of data on important modifying genotypes such as HbS; alpha-thalassemia 3.7 deletion, as well as data on ART; its adherence; and CD4 count is a limitation of this study." (PMID 32802082, 2020).
alveolar proteinosis (1 paper, 2022). "This would be the first reported case according to our knowledge, of a patient who normalizes CD4 count after antifungal treatment, later developing alveolar proteinosis due to M." (PMID 35314651, 2022).
anal disease (1 paper, 2025). "Factors associated with an increased risk of HSIL recurrence in the cancer group were extensive anal disease, CD4 counts < 500, and lack of adjuvant radiation." (PMID 40427143, 2025).
Anal fistula (1 paper, 2022). An abnormal connection between the epithelialised surface of the anal canal and the perianal skin. "Through data collection and immunofluorescence experiments, it was found that the number of CD4+ lymphocytes in the wound granulation tissue of anal fistula patients was negatively correlated with the healing time, while the increased number of CD8+ lymphocytes delayed the healing time." (PMID 36016687, 2022).
anal tumors (1 paper, 2024). "None of the mice in the SQV or control groups developed overt anal tumors, except three mice that were CD4-depleted." (PMID 39339897, 2024). "Over the 20-week treatment period, three of the CD4 T cell-depleted control mice (3/22) developed overt anal tumors compared to none of the vehicle control mice (0/20) (p-value = 0.09)." (PMID 39339897, 2024). "In comparison to the CD4-depleted control mice (3/22), none of the CD4-depleted mice treated with SQV developed overt anal tumors (0/16) (p-value = 0.1299)." (PMID 39339897, 2024).
and-neck malignant tumor (1 paper, 2020). "Furthermore, KIF20A-derived long peptides were identified bearing naturally processed epitopes recognized by CD4(+) T cells and CTLs, which induce tumor-specific T-helper type 1 (TH1) cells and CTLs in head-and-neck malignant tumor tissues." (PMID 32322170, 2020).
anhidrosis (1 paper, 2021). Lack of sweating or the ability to sweat when provoked by the appropriate stimulus. "It has been reported that both CD4+ and CD8+ T cells infiltrate around eccrine gland epithelial cells in AIGA and CholU with anhidrosis/hypohidrosis." (PMID 34445091, 2021).
aortic regurgitation (1 paper, 2012). "One of the patients in our study, with a CD4 of 171/μl, had aortic root dilatation, which was associated with severe aortic regurgitation." (PMID 22907266, 2012).
Apathy (1 paper, 2022). Apathy is a quantitative reduction of interest, motivation and the initiation and persistence of goal-directed behavior, where often the accompanying emotions, thoughts, and social interactions are also diminished. "Apathy scores did not correlate with current (r=0.0353, p=0.610) or nadir CD4+ T cells (r=0.00936, p=0.893), or plasma viral suppression (suppressed 2.058±2.60 versus unsuppressed 2.61±2.99, p=0.0990)." (PMID 37205974, 2022).
arenavirus infection (1 paper, 2010). "Given that CD4+ T cells are essential for maintaining effective CTL responses during an arenavirus infection, knowledge of human CD4+ T cell epitopes is a crucial step in the development of an arenavirus vaccine that induces effective T cell-mediated immunity." (PMID 20478058, 2010).
ataxia telangiectasia (1 paper, 2022). Ataxia-telangiectasia is the association of severe combined immunodeficiency (affecting mainly the humoral immune response) with progressive cerebellar ataxia. "Literature showed that high levels of AFP in children with suspected chronic ataxia, along with a profile of low levels of IgA, IgE, and IgG and a low lymphocyte count (CD4+ and CD8+), is suggestive of and supports an early diagnosis of Ataxia telangiectasia." (PMID 36267884, 2022).
atrophic thyroiditis (1 paper, 2025). Atrophic thyroiditis is an organ-specific autoimmune disease characterized by thyroid autoantibodies, functional hypothyroidism, and absence of goiter. "In contrast, atrophic thyroiditis is characterized by the activation of Th2 CD4+ T helper lymphocytes, which assist B lymphocytes in producing TRAb." (PMID 40900474, 2025).
Autosomal dominant hyper-IgE syndrome (1 paper, 2013). 2000 IU/ml), recurring staphylococcal skin abscesses, and recurrent pneumonia with formation of pneumatoceles. "However, naive CD4 T cells from patients with STAT3 mutations causing autosomal dominant hyper-IgE syndrome (AD-HIES) were recently shown to be unable to acquire B cell help activity when stimulated in the presence of STAT3 activating cytokines." (PMID 23923047, 2013).
Batten disease (1 paper, 2026). "The Cln3 gene, prioritised in our analysis for CD risk in ILC3s but not in CD4+ T cells, underlies the majority of cases of the neurodevelopmental disorder Batten disease." (PMID 41573945, 2026).
Bell's palsy (1 paper, 2025). Partial or complete paralysis of the facial muscles of one side of a person's face. "In addition, in the acute phase of Bell’s palsy, a decrease in the percentage of total T cells (CD3) and T helper (CD4) was observed compared to the control group." (PMID 40299566, 2025).
BENTA (1 paper, 2023). "Individuals with BENTA disease have normal numbers of circulating CD4 and CD8 T cells, but to our knowledge no detailed T cell immunophenotyping has been reported." (PMID 36960072, 2023).
biotin deficiency (1 paper, 2023). "Studies have shown that some chronic inflammatory diseases are associated with biotin deficiency, and biotin deficiency can enhance the inflammatory response of CD4+ T cells." (PMID 37780858, 2023).
Blau syndrome (1 paper, 2020). Blau syndrome (BS) is a rare systemic inflammatory disease characterized by early onset granulomatous arthritis, uveitis and skin rash. "As with Nod2−/− memory T cells in mice, which showed increased expression of Ccr7 in response to TCR-ligation, CD3/CD28 stimulation also increased expression of CCR7 on CD4+ T cells similarly in both the patients with Blau syndrome compared to healthy controls." (PMID 33106495, 2020). "Interestingly, CD4+ T cells from two Blau syndrome patients show elevated IL-17 and increased CCR7." (PMID 33106495, 2020).